MBOAT2 (membrane bound glycerophospholipid O-acyltransferase 2)
Description:
Acyltransferase which catalyzes the transfer of an acyl group from an acyl-CoA to a lysophospholipid leading to the production of a phospholipid and participates in the reacylation step of the phospholipid remodeling pathway also known as the Lands cycle. Catalyzes preferentially the acylation of lysophosphatidylethanolamine (1-acyl-sn-glycero-3-phosphoethanolamine or LPE) and lysophosphatidic acid (LPA) and to a lesser extend lysophosphatidylcholine (LPC) and lysophosphatidylserine (LPS). Prefers oleoyl-CoA as the acyl donor. May be involved in chondrocyte differentiation (By similarity).
Synonyms: LPAAT; LPCAT; LPEAT; LPLAT 2; OACT2; FLJ14415; FLJ90298; LPLAT13
Tractability: Antibody: UniProt predicts a signal peptide or a membrane-spanning region. PROTAC: ubiquitination databases record sites on it; its protein half-life has been measured.
Gene: Protein-coding gene on chromosome 2 (8,852,690 to 9,003,747, reverse strand). Ensembl gene ENSG00000143797.
Subcellular location: Endoplasmic reticulum membrane
Subcellular location (Human Protein Atlas): Vesicles
Pathways (Reactome):
Metabolism: Acyl chain remodelling of PC; Acyl chain remodelling of PE
Gene Ontology:
Molecular function: 1-acylglycerol-3-phosphate O-acyltransferase activity; 1-acylglycerophosphocholine O-acyltransferase activity; 1-acylglycerophosphoethanolamine O-acyltransferase activity; 1-acylglycerophosphoserine O-acyltransferase activity; 2-acylglycerol-3-phosphate O-acyltransferase activity; 1-alkenylglycerophosphoethanolamine O-acyltransferase activity; plasmalogen synthase activity
Biological process: phosphatidylcholine acyl-chain remodeling; phosphatidylethanolamine acyl-chain remodeling; phosphatidylserine acyl-chain remodeling; lipid modification; regulation of chondrocyte differentiation; phospholipid metabolic process
Cellular component: endoplasmic reticulum membrane; membrane
Genetic constraint (gnomAD): Loss-of-function variants: 19 observed, 44.99 expected, observed/expected ratio (o/e) 0.42, 90% interval 0.29 to 0.62. The upper end of that interval is the gene's LOEUF score, 0.62, which puts it in group 2 of 6, group 1 being the genes least tolerant of losing a copy. Missense variants: 374 observed, 473.8 expected, observed/expected ratio (o/e) 0.79, 90% interval 0.72 to 0.86. Synonymous variants: 174 observed, 176.04 expected, observed/expected ratio (o/e) 0.99, 90% interval 0.87 to 1.12.
Homologues: Orthologues: chimpanzee MBOAT2 (99% identical), macaque MBOAT2 (99% identical), dog MBOAT2 (91% identical), pig MBOAT2 (90% identical), rat Mboat2 (87% identical), mouse Mboat2 (87% identical), rabbit MBOAT2 (83% identical), guinea pig MBOAT2 (78% identical), tropical clawed frog mboat2 (71% identical), zebrafish mboat2a (60% identical), zebrafish mboat2b (57% identical), Drosophila melanogaster oys (39% identical), and 2 more. Paralogues in human: MBOAT1 (51% identical), MBOAT7 (22% identical), LPCAT3 (20% identical), MBOAT4 (20% identical), PORCN (16% identical).
Diseases named in the same sentence as MBOAT2 in open-access papers:
MBOAT2 is named in the same sentence as 44 diseases in open-access papers, as found by Europe PMC text mining. Sharing a sentence is not in itself a finding about the gene and the disease. The quoted sentences say what the papers report.
pancreatic cancer (11 papers, 2021 to 2025). "In pancreatic cancer, higher MBOAT2 expression levels are associated with a worse prognosis due to increased proliferation in cancer cells, as demonstrated in experiments with pancreatic cancer cells." (PMID 38893234, 2024). "MBOAT2, exactly Circ-MBOAT2 (Circular RNA/CircRNA bound MBOAT2), was significantly upregulated in pancreatic cancer tissues compared to normal tissues and associated with pancreatic cancer progression." (PMID 38741142, 2024). "MBOAT2 is implicated in cancer, with upregulated expression in pancreatic cancer, invasive breast cancer, cholangiocarcinoma, and prostate adenocarcinoma." (PMID 38893234, 2024). "Based on the expression property and biological function of circ-MBOAT2 in pancreatic cancer, circ-MBOAT2-associated miRNAs should exhibit low expression and anti-cancer role in pancreatic cancer." (PMID 33832516, 2021). "In this study, it was found that the expression of circ-membrane bound O-acyltransferase domain containing 2 (circ-MBOAT2) was significantly increased in pancreatic cancer specimen and cells; however, the underlying mechanism was still unclear." (PMID 33832516, 2021). "Likewise, MBOAT2 has been shown to be noticeably elevated in pancreatic tumors and was linked to EMT, cancer cell proliferation, migration, grade, recurrence, and poor prognosis." (PMID 39682235, 2024). "And MBOAT2 is an acyltransferase and previously found to be associated with multiple diseases like cardiomyopathy, multiple sclerosis, adrenomyeloneuropathy, and pancreatic Cancer." (PMID 36820206, 2023). "All in all, we found circ-MBOAT2 silencing repressed pancreatic cancer progression via regulating cell proliferation, apoptosis, migration, invasion through repressing glutamine catabolism, and the underlying mechanism was that circ-MBOAT2 induced GOT1 expression via absorbing miR-433-3p." (PMID 33832516, 2021). "Circ-MBOAT2 acted as a sponge of miR-433-3p, which was associated with GOT1 and repressed cell proliferation, migration, invasion, and glutamine catabolism in pancreatic cancer." (PMID 38612727, 2024). "In pancreatic cancer tissues and cells, circ-MBOAT2 and GOT1 expression were significantly upregulated, while miR-433-3p expression was downregulated." (PMID 38612727, 2024). "In pancreatic cancer, MBOAT2 overexpression increases CDK2 and CCNA2 expression levels, causing the cell cycle to advance from the G1 to the G2 phase." (PMID 37240761, 2023). "In the literature, it has been shown that circ-MBOAT2 controls the growth of pancreatic cancer tumors and glutamine catabolism." (PMID 37240761, 2023). "The level of MBOAT2 was remarkably upregulated in most tumors, especially pancreatic tumors, and was positively correlated with a greater rate of tumor recurrence, higher histologic grade, and worse overall survival." (PMID 35571489, 2022). "The role of circ-MBOAT2 in modulating tumor development and glutamine catabolism in pancreatic cancer has been confirmed in the literature." (PMID 35664305, 2022). "Circ-MBOAT2 silencing repressed cell proliferation, migration, invasion and glutamine catabolism, whereas promoted cell apoptosis in pancreatic cancer." (PMID 33832516, 2021). "MiR-433-3p inhibitors hindered circ-MBOAT2 silencing-mediated impacts on pancreatic cancer progression and glutamine catabolism." (PMID 33832516, 2021). "Herein, circ-MBOAT2 was also shown to be apparently upregulated in the tissue and cell samples of pancreatic cancer, and circ-MBOAT2 expression was higher in stage III-IV pancreatic cancer tissues than in stage I-II." (PMID 33832516, 2021). "The underneath mechanism by which circ-MBOAT2 regulated pancreatic cancer process was continued to be unveiled." (PMID 33832516, 2021). "These evidences confirmed circ-MBOAT2 regulated malignant properties of pancreatic cancer by sponging miR-433-3p." (PMID 33832516, 2021). "Further study of MBOAT2 could provide new ideas about the carcinogenesis and treatment of pancreatic cancer (PC)." (PMID 35571489, 2022).
pancreatic cancer (continued). "In particular, the underlying role of MBOAT2 and its potential mechanisms in pancreatic cancer have not yet been explored." (PMID 35571489, 2022). "Furthermore, rescue experiments were performed to determine the effects of circ-MBOAT2 overexpression on si-circ-MBOAT2-mediated pancreatic cancer cell processes." (PMID 33832516, 2021). "Whether circ-MBOAT2 modulated pancreatic cancer process via sponging miR-433-3p was further revealed." (PMID 33832516, 2021). "Whether circ-MBOAT2 could mediate pancreatic cancer growth via absorbing miR-433-3p was further explored in this study." (PMID 33832516, 2021). "Additionally, qRT-PCR data displayed that circ-MBOAT2 expression was higher in stage III-IV pancreatic cancer tissues than in stage I-II." (PMID 33832516, 2021). "Circ-MBOAT2 expression was firstly determined in the tissues and cells of pancreatic cancer." (PMID 33832516, 2021). "However, the effects of circ-membrane bound O-acyltransferase domain containing 2 (circ-MBOAT2) on regulating pancreatic cancer process were unclear." (PMID 33832516, 2021). "The study continued to explore that whether circ-MBOAT2 regulated the development of pancreatic cancer." (PMID 33832516, 2021). "Thus, these evidences illustrated circ-MBOAT2 could regulate pancreatic cancer development and glutamine metabolism by absorbing miR-433-3p." (PMID 33832516, 2021). "We analyzed the mRNA expression levels of the MBOAT2/CDA/LPCAT2/B4GALT5 genes in PACA patient samples and pancreatic cancer cells." (PMID 37240761, 2023). "Circ-MBOAT2 modulated tumor development and glutamine catabolism by miR-433-3p/GOT1 axis in pancreatic cancer." (PMID 33832516, 2021). "Circ-MBOAT2 and GOT1 expression were significantly upregulated, while miR-433-3p expression was downregulated in pancreatic cancer tissues and cells compared with normal pancreatic tissues or cells." (PMID 33832516, 2021). "It is proposed that MBOAT2, CDA, LPCAT2 and B4GALT5 expression may promote the onset and progression of pancreatic cancer." (PMID 37240761, 2023). "Zhou reported that circ-MBOAT2 modulates tumor development and glutamine catabolism via the miR-433-3p/GOT1 axis in pancreatic cancer, suggesting circ-MBOAT2 may be a therapeutic target for pancreatic cancer." (PMID 40564276, 2025). "The mRNA levels of MBOAT2, CDA, LPCAT2 and B4GALT5 were significantly higher in PACA cells than in normal human pancreatic duct epithelial cells, implying that the high expression levels of these four genes may promote the development and progression of pancreatic cancer." (PMID 37240761, 2023). "Membrane-bound O-acyltransferase domain containing 2 (MBOAT2) gene in EC had not been reported, but some research results showed that MBOAT2 was a likely proto-oncogene in pancreatic cancer, which could foresee predict the prognosis of pancreatic cancer patients." (PMID 39170242, 2024).
prostate carcinoma (5 papers, 2019 to 2024). A carcinoma that arises from epithelial cells of the prostate gland. "Research has indicated that AR antagonists sensitize AR+ prostate cancer to ferroptosis by downregulating MBOAT2." (PMID 39097593, 2024). "Previous study has illustrated that circ-MBOAT2 acted as an oncogene in tumor growth in prostate cancer." (PMID 33832516, 2021). "This study aimed to characterize one circRNA derived from the MBOAT2 gene and termed it circMBOAT2, which has been reported to promote prostate cancer progression." (PMID 32796815, 2020). "The research also suggests that AR and ER transcriptionally upregulate the expression of MBOAT1 and MBOAT2, respectively, and inhibition of these receptors downregulates their transcriptional expression, sensitizing prostate cancer and breast cancer cells to ferroptosis." (PMID 37735316, 2023). "MBOAT2 exhibited specific upregulation in prostate cancer and its expression was positively correlated with androgen receptor (AR) mRNA expression in prostate cancer, suggesting that MBOAT2 may be a target of AR in prostate cancer cells." (PMID 37735316, 2023). "In validation of its elevated AR consensome ranking, we confirmed that MBOAT2 was an AR-regulated gene in cultured prostate cancer cell lines, and that depletion of MBOAT2 significantly increased LNCaP cell numbers at growth day 5 in in R1881-treated celIs, but not untreated cells." (PMID 31672983, 2019). "Moreover, AR antagonists could increase the sensitivity of AR-positive prostate cancer cells to ferroptosis by downregulating MBOAT2 directly." (PMID 37735316, 2023). "Therefore, we conducted WB validation for GPX4 and MBOAT2 simultaneously and found that AR indeed enhances MBOAT2 rather than GPX4 in prostate cancer." (PMID 39097593, 2024).
uveal melanoma (4 papers, 2022 to 2025). A melanoma derived from melanocytes of the uveal tract. "High MBOAT2 expression correlates with a worse prognosis in several cancers, including PC, adrenocortical carcinoma, mesothelioma, uveal melanoma, and urothelial carcinoma, yet it is associated with longer survival in kidney renal clear cell carcinoma." (PMID 35571489, 2022). "In cases of adrenocortical carcinoma, hepatocellular carcinoma, bladder urothelial carcinoma, endometrial carcinoma, pheochromocytoma and uveal melanoma, high mRNA levels of MBOAT2 can make a poor prognosis more likely." (PMID 37240761, 2023). "Furthermore, within the scope of the same study, a set of genes including DERL1, FBXL17, MBOAT2,PLAG, SLC7A, and YTHDF3 were identified as target genes susceptible to modulation by miR-181b-5p in tumor tissue of uveal melanoma patients." (PMID 38914847, 2025). "Furthermore, the GEPIA database demonstrated that MBOAT2 overexpression was connected to a worse prognosis in pancreatic adenocarcinoma, mesothelioma, uveal melanoma, urothelial carcinoma, and adrenocortical carcinoma but was associated with longer survival in kidney renal clear cell carcinoma." (PMID 35571489, 2022).
hypertrophic obstructive cardiomyopathy (3 papers, 2021 to 2023). "A membrane-bound O-acyltransferase domain on chromosomal band 2p25.1, known as MBOAT2, is mainly linked to adrenergic disorders, hypertrophic obstructive cardiomyopathy and multiple sclerosis." (PMID 37240761, 2023). "Related to cardiomyopathies, a set of circulating circRNAs DNAJC6, TMEM56, and MBOAT2 has been proposed to discriminate between healthy and hypertrophic cardiomyopathy." (PMID 34498126, 2021). "In addition, serum circRNAs DNAJC6, TMEM56, and MBOAT2 were decreased in hypertrophic obstructive cardiomyopathy patients." (PMID 37323876, 2023). "Circulating circRNAs DNAJC6, TMEM56, and MBOAT2 were suggested as biomarkers for hypertrophic obstructive cardiomyopathy, whereas circulating circRNA_004183, circRNA_079265, and circRNA_105039 might be used for the diagnosis of congenital heart disease in children." (PMID 37323876, 2023).
pancreatic ductal adenocarcinoma (3 papers, 2022). An infiltrating adenocarcinoma that arises from the epithelial cells of the pancreas. "Real-time quantitative polymerase chain reaction and western blot analysis were performed to determine the level of MBOAT2 in pancreatic ductal adenocarcinoma (PDAC) cell lines." (PMID 35571489, 2022). "MBOAT2 overexpression in pancreatic ductal adenocarcinoma (PDAC) has been related to a poor prognosis." (PMID 36685915, 2022). "The results of previous studies were consistent with the results of this study, indicating that MBOAT2 was overexpressed in the neoplastic epithelia of pancreatic ductal adenocarcinoma and was inversely correlated with patient survival." (PMID 35664305, 2022).
pheochromocytoma (3 papers, 2022 to 2023). "In addition, using the GEPIA database, we found that the MBOAT2 level was dramatically higher in pancreatic adenocarcinoma, breast invasive carcinoma, prostate adenocarcinoma, cholangiocarcinoma, pheochromocytoma, paraganglioma, and brain lower-grade glioma." (PMID 35571489, 2022).
fatty liver (2 papers, 2013 to 2022). "We found that miR-130a-5p was downregulated in the liver of laying hens with fatty liver, targeting the expression of MBOAT2." (PMID 36552896, 2022). "Based on these findings, the inhibition of MBOAT2 activity or up-regulation of miR-130a-5p is of utmost importance when designing liver-protective therapies to attenuate fatty liver disease." (PMID 36552896, 2022).
acute myeloid leukemia (1 paper, 2022). Acute myeloid leukemia (AML) is a group of neoplasms arising from precursor cells committed to the myeloid cell-line differentiation. "However, MBOAT2 expression was notably lower in lymphoid neoplasm diffuse large B-cell lymphoma, thymoma, kidney chromophobe, acute myeloid leukemia, kidney renal clear cell carcinoma, and skin cutaneous melanoma." (PMID 35571489, 2022).
breast carcinoma (1 paper, 2023). "Collectively, these findings highlight MBOAT1 and MBOAT2 as promising targets for prostate and breast cancers." (PMID 37735316, 2023).
gastritis (1 paper, 2023). Inflammation of the stomach. "In this study, we screened 11 important lncRNAs (AFAP1-AS1, MIR155HG, LINC00472, and FAM201A) and mRNAs (CASP10, SLC26A2, TRIB1, BMP2K, SCAMP1, TNKS1BP1, and MBOAT2) according to the gene expression profiles of gastric epithelial tissues in different stages of Hp infection-induced gastritis." (PMID 37249580, 2023).
Nivelon-Nivelon-Mabille Syndrome (1 paper, 2022). "Of these, four genes were determined to be related to bone development (PLXNA2 with prognathism, HHAT with the complex Nivelon-Nivelon-Mabille Syndrome, MBOAT2 with chondrocyte differentiation, and ITGAV with chondrodystrophy), and one to calcium homeostasis (HPCAL1)." (PMID 36230363, 2022).
Obesity (1 paper, 2022). Accumulation of substantial excess body fat. "We also analyzed the expression of FBXW7, MBOAT2, STXBP4, SPARCL1, and UTS after SLFN12 overexpression because these are obesity-related genes." (PMID 36291149, 2022).
cancer (11 papers, 2021 to 2025). A tumor composed of atypical neoplastic, often pleomorphic cells that invade other tissues. "Considering circRNAs serving as sponge of miRNAs to regulate cancer evolution, we further sought the miRNA associated with circ-MBOAT2." (PMID 33832516, 2021). "Our findings also demonstrate the prognostic significance of MBOAT2 expression in several human cancers, though the exact nature of the association may vary by cancer type." (PMID 35571489, 2022). "Subsequently, the researchers investigated the factors driving the upregulation of MBOAT1 and MBOAT2 in cancer." (PMID 37735316, 2023). "Our study suggests that the MBOAT2 level is an essential and potential prognostic biomarker in various cancers, especially PC." (PMID 35571489, 2022). "Limited research on the role of membrane-bound O-acyltransferase domain–containing 2 (MBOAT2) in cancer biology exists." (PMID 35571489, 2022). "Limited research on the potential and possible function of MBOAT2 in cancer biology exists at this time." (PMID 35571489, 2022). "In this study, we first comprehensively analyzed the expression level of MBOAT2 and its possible correlation with prognosis in different types of cancers, including PC." (PMID 35571489, 2022). "Our study demonstrated that the MBOAT2 level is deregulated in and closely related to the prognosis of several human cancers." (PMID 35571489, 2022). "These insights establish TLKs as pharmacologically exploitable targets in ALT-driven tumors and chromosomally unstable cancers, while providing mechanistic context for understanding how the circ-MBOAT2 coordinates immune evasion in NSCLC pathogenesis through TLK1-dependent regulation." (PMID 40369698, 2025).